SOX3 (SRY-box transcription factor 3)
Diseases named in the same sentence as SOX3 in open-access papers (continued):
Sharing a sentence is not in itself a finding about the gene and the disease.
glioma (9 papers, 2011 to 2024). A benign or malignant brain and spinal cord tumor that arises from glial cells (astrocytes, oligodendrocytes, ependymal cells). "Additionally, the expression of SOX3 was associated with the presence of the cell cycle marker Ki67, reinforcing its pivotal role in maintaining glioma cells in a proliferative state and promoting malignant behavior in GBM cells." (PMID 38927713, 2024). "In keeping with these findings, misexpression of Sox3 has previously been demonstrated to cause oncogenic transformation of embryonic fibroblasts whereas microRNA-mediated suppression of Sox2 decreases the capacity of glioma cells to contribute to tumor growth." (PMID 21483788, 2011). "They transfected primary cultures derived from human grade IV gliomas with vectors expressing either full-length SOX3 or a dominant negative version of SOX3 (SOX3EnR-Myc)." (PMID 38927713, 2024). "Glioma cells expressing SOX3 showed the presence of cell cycle marker Ki67 within 24 h following transfection." (PMID 38927713, 2024). "Consistent with the previous findings (above), the mRNA levels of SOX2 and SOX3 were higher in glioma cell lines compared to other cancer types." (PMID 34953010, 2022). "Other reports have shown similar mechanisms, which suggested long noncoding RNA SOX2OT upregulated transcription factor SOX3 expression by down-regulating miR-194-5p or miR-122 in glioma cells." (PMID 30691465, 2019). "Western blotting was performed to analyze the expression of SOX3 in human glioma tissues, GBM cells and GSCs." (PMID 29132362, 2017). "SOX3 expression was obviously up-regulated in glioma tissues compared with NBTs and up-regulated in high-grade glioma tissues compared with low-grade glioma tissues." (PMID 29132362, 2017). "Our study demonstrated that SOX3 was increased in glioma tissues and GSCs, and increased with an increase in glioma grade." (PMID 29132362, 2017). "In order to elucidate whether the expression of SOX2 and SOX3 affected the proliferation and invasion of glioma cells, we downregulated the expression of SOX2 and SOX3 to observe the changes of migration and invasion ability of U251 cells." (PMID 34953010, 2022). "The possible interaction between TGF-β (GDNF) and SOXB1 (SOX1, SOX2, SOX3) family members might explain the difficulties in regulating glioma stem cell recurrence after surgical tumor resection and drug resistance." (PMID 35392088, 2022). "In addition, the expression of SOX3 in U87 and U251 glioma cell lines was higher than that in HA cells, but lower than that in GSC-U87 and GSC-U251 cells." (PMID 29132362, 2017). "Thus, as in the developing CNS Sox3 has the capacity to maintain glioma cells in an undifferentiated and proliferating state, whereas active repression of Sox3 target genes causes cells to exit the cell cycle." (PMID 21483788, 2011). "To examine if Sox3 has a similar regulatory capacity in glioma cells as in NSCs, we transfected primary cultures derived from human grade IV gliomas with vectors expressing either full-length Sox3, a dominant negative version of Sox3 (Sox3EnR-Myc) or enhanced GFP (EGFP)." (PMID 21483788, 2011). "Although our results indicate that the capacity of Sox3 to hinder differentiation is conserved between glioma cells and NSCs, further studies will be necessary to explain the exact role of Oct4, Nanog and Klf4 in gliomas." (PMID 21483788, 2011). "The redundancy between members of the SOXB1 subgroup enhances their interactions with other genes involved in the renewal and proliferation of glioma stem cells (SOX1, SOX2, and SOX3)/Cdks/cyclins." (PMID 35392088, 2022). "SOX3 and TDGF-1 was upregulated in glioma tissues and cell lines and their expression increased as the pathological grade increased." (PMID 29132362, 2017). "In contrast, glioma cells transfected with the non-functional SOX3 were prompted to exit the cell cycle, resulting in a reduction of cells positive for Ki67 after 24 h." (PMID 38927713, 2024).
glioma (continued). "SOX3 and TDGF-1 were both upregulated in human glioma tissues and GSCs." (PMID 36803831, 2023). "SOX3 and TDGF-1 were up-regulated in human glioma tissues and GSCs." (PMID 29132362, 2017). "SOX3 and SOX2OT were highly expressed in glioma tissues and GSCs." (PMID 29132362, 2017). "The relationship between SOX3 and glioma has not been reported." (PMID 29132362, 2017). "We also demonstrated that Sox3 had similar effect in NSCs as in glioma cells and and block cell cycle exit, whereas its dominant negative version promote cell cycle exit in both NSCs and glioma cells." (PMID 21483788, 2011).
gastric cancer (7 papers, 2020 to 2026). A primary or metastatic malignant neoplasm involving the stomach. "The validation study showed that SOX3 is overexpressed in cancer tissues, and its levels are associated with poor outcomes for stomach cancer, and that SOX3 promotes gastric cancer cell invasion and migration through MMP9." (PMID 32363730, 2020). "Our study demonstrated that SOX3 is highly expressed in gastric cancer tissues and is associated with poor outcomes for gastric cancer." (PMID 32363730, 2020). "Loss‐of‐function studies showed that SOX3 promotes gastric cancer cell invasion and migration in vitro and in vivo, and it exerts little effects on cell proliferation." (PMID 32363730, 2020). "Kaplan‐Meier survival analysis of these 304 patients showed that the OS of gastric cancer patients was negatively associated with the SOX3 levels in tumour tissue (P = .0002)." (PMID 32363730, 2020). "Loss‐of‐function showed that SOX3 promoted gastric cancer cell invasion and migration in vitro and in vivo." (PMID 32363730, 2020). "Notably, an increase in SOX3 expression has been associated with gastric cancer characterized by lymph node metastasis, primary tumor invasion, and a high TNM tumor graduation system." (PMID 38927713, 2024). "In gastric cancer (GC), there is an observed elevation in serum SOX3 expression compared to healthy individuals." (PMID 38927713, 2024). "Increased migration secondary to SOX3 downregulation in gastric cancer has been shown, with the opposite shown in osteosarcoma in which downregulation of SOX3 decreased the snail/twist axis." (PMID 38132437, 2023). "To investigate the effects of SOX3 on gastric cancer cells, we generated gastric adenocarcinoma cells with SOX3 silence using shRNA against SOX3, MKN45‐SOX3low and AGS‐SOX3low." (PMID 32363730, 2020). "We further probed the mechanisms under the effects of SOX3 on gastric cancer cell invasion and migration preliminarily." (PMID 32363730, 2020). "Serum levels of SOX3, one of down‐regulated proteins, in stomach cancer patients were higher than in healthy controls." (PMID 32363730, 2020). "We further revealed the potentiality of SOX3 level in the serums and in the tumour tissues as a prognostic marker for gastric carcinoma patients." (PMID 32363730, 2020). "SOX3 promotes the progression of gastric cancer and osteosarcoma." (PMID 39889187, 2025). "We further demonstrated SOX3 as a candidate prognostic marker for gastric cancer." (PMID 32363730, 2020). "We then evaluated the clinical relevance of the serum SOX3 levels in gastric cancer patients." (PMID 32363730, 2020). "Our study highlights the potentiality of the paired pre‐ and post‐operation serum proteome signatures for the detection of biomarkers and reveals that SOX3 may serve as a candidate prognosis marker for gastric cancer." (PMID 32363730, 2020). "Furthermore, immunoblotting assays and IHC studies showed that the SOX3 levels in gastric cancer tissues were higher than that in corresponding non‐cancerous mucosae (P = .043)." (PMID 32363730, 2020). "Our preliminary results demonstrated for the first time that SOX3 expression in the serums and in the tumour tissues may serve as a candidate marker for prognosis and outcomes of gastric carcinoma patients." (PMID 32363730, 2020). "We considered SOX3 expression may influence extracellular matrix in gastric cancer." (PMID 32363730, 2020). "In summary, this study highlights the potentiality of the paired pre‐ and post‐operation serum proteome signature for the detection of putative biomarkers for gastric carcinoma and reveals that SOX3 may serve as a candidate molecular marker for prognosis and outcomes of gastric cancer patients." (PMID 32363730, 2020). "However, the role of SOX3 in stomach carcinoma remains uncertain." (PMID 32363730, 2020). "For example, in gastric cancer, RG3 mitigates cisplatin resistance via upregulation of miRNA-429 and suppression of SOX3 and the PI3K/Akt/mTOR axis." (PMID 41501793, 2026).
gastric cancer (continued). "The serum SOX3 level was also much higher in advanced cancer patients (824.42 ± 39.01 pg/mL, N = 55) than in early cancer patients (573.39 ± 62.61 pg/mL, N = 5) (P = .039), and IHC study showed that SOX was highly expressed in advanced gastric cancer tissues compared with that in early tumour." (PMID 32363730, 2020).
osteosarcoma (7 papers, 2019 to 2026). A usually aggressive malignant bone-forming mesenchymal neoplasm, predominantly affecting adolescents and young adults. "An explanation for the correlation between SOX3 expression and the proliferative index in oral canine melanomas may be based on the fact that SOX3 is associated with cell cycle regulation similar to that observed in osteosarcoma cells." (PMID 41012776, 2025). "Although the specific role of SOX3 in NSCLC remains largely unexplored, aberrant expression of SOX3 has been reported in other malignancies such as osteosarcoma and breast cancer." (PMID 41268614, 2026). "Knockdown experiments with SOX3 resulted in a G1 arrest in OS cells, accompanied by a decrease in the proportion of osteosarcoma MG63 and U2OS cells in the S and G2/M phases." (PMID 38927713, 2024). "In a study involving osteosarcoma patients (n = 70), higher gene (RT-qPCR) and protein expression of SOX3 were observed when compared to benign bone lesions." (PMID 38927713, 2024). "Additionally, in vitro studies using osteosarcoma cell lines indicated that silencing SOX3 expression in osteosarcoma leads to reduced aggressiveness, including proliferation and invasion." (PMID 38927713, 2024). "This identifies SOX3 as a potential therapeutic target for metastasis in osteosarcoma." (PMID 38927713, 2024).
panhypopituitarism (5 papers, 2018 to 2024). Insufficient production of all the anterior pituitary hormones. "Duplications of the SOX3 and polyalanine tract expansions of the C‐terminal domain of SOX3 have been linked to septo‐optic dysplasia, ID, and panhypopituitarism." (PMID 30264515, 2018). "Mutations affecting SOX3 are associated with panhypopituitarism in mice and humans, however the etiology of this was unknown." (PMID 39325695, 2024). "In addition to gonad development, Sox3 was associated with X-linked mental retardation, growth hormone deficiency and X-linked panhypopituitarism in humans, and was required for the functions of pituitary and formation of midline structures in central nervous system in mice." (PMID 30588557, 2019).
breast carcinoma (4 papers, 2023 to 2026). "In contrast, SOX3 was shown to upregulate pro-apoptotic genes in breast cancer and was associated with a poor prognosis." (PMID 37509311, 2023). "In summary, the action of SOX3 in BC, whether as an oncogenic or tumor suppressor, appears to be linked and dependent on the breast cancer histological, molecular, and grade subtype." (PMID 38927713, 2024). "In breast cancer cell lines, it is suggested that SOX3 expression is related to epithelial–mesenchymal transition, generating implications in tumor biology and contributing to metastatic formation." (PMID 41012776, 2025). "These disparate results highlight the complex and context-dependent role of SOX3 in the regulation of apoptosis across different molecular subtypes of breast cancer." (PMID 38927713, 2024). "This aligns with earlier studies that identified elevated levels of SOX3 as key to inhibiting EMT, as seen by the reduced expression of SNAIL in the MCF-7 breast cancer cell line." (PMID 38927713, 2024). "In contrast, a recent study in breast cancer, utilizing the MDA-MB-231 cell line from invasive ductal carcinoma of the triple negative (TN) molecular subtype and characterized by undifferentiated epithelial cells with mesenchymal morphology, revealed no SOX3 expression." (PMID 38927713, 2024).
congenital hypopituitarism (4 papers, 2012 to 2024). "We have shown previously that duplication of SOX3 in 46 XY males is associated with CNS defects and congenital hypopituitarism." (PMID 22291885, 2012). "Over-expression or under-expression of SOX3 can lead to similar clinical manifestations, including isolated GH defciency, congenital hypopituitarism, with or without intellectual impairment." (PMID 38383389, 2024). "The variant of SOX3 often manifested as X-linked hypopituitarism with various clinical manifestations, including isolated GH deficiency (IGHD), congenital hypopituitarism (CH), etc., with or without mental retardation." (PMID 35114986, 2022).
Septo-optic dysplasia (4 papers, 2014 to 2021). Septooptic dysplasia (SOD) is a clinically heterogeneous disorder characterized by the classical triad of optic nerve hypoplasia, pituitary hormone abnormalities and midline brain defects. "In septo-optic dysplasia there are few family cases, the majority of cases being sporadic; thus, less than 1% of septo-optic dysplasia patients have mutations in the genes Hesx1, Sox2, Sox3, or Otx2." (PMID 33324176, 2020). "Besides, mice with mutations in Sox2 or Sox3, used as animal models of septo-optic dysplasia, display downregulation of Shh expression." (PMID 33324176, 2020). "Indeed, mutations in signaling molecules (e.g., SHH and FGFs) and transcription factors (e.g., SIX3, SOX2, and SOX3) have been implicated in midline forebrain defects such as septo-optic dysplasia and holoprosencephaly." (PMID 33324176, 2020).
cleft lip (3 papers, 2021 to 2024). Congenital defect in the upper lip where the maxillary prominence fails to merge with the merged medial nasal prominences. "For example, one study reported increased SOX3-positive immunoreactive structures within human unilateral cleft lip." (PMID 38227085, 2024). "Information about the role of SOX3 involvement in the development of cleft lip is limited, but together with other SOX genes it contributes to the correct formation of facial structures during embryonic development." (PMID 33917041, 2021). "Furthermore, increased SOX3-positive immunoreactive structures within human unilateral cleft lip have been reported." (PMID 38227085, 2024). "Increase of SOX3 positive structures within patient epithelium could indicate a possible involvement of SOX3 in the formation of unilateral cleft lip possibly by affecting cell proliferation within the cleft-affected tissue." (PMID 33917041, 2021). "The statistically significant differences found in all evaluated cleft tissue types indicate that SOX3 might be involved with the regulatory mechanisms of postnatal cleft lip and cleft palate tissue differentiation by possibly affecting tissue growth and proliferation locally in these regions." (PMID 37366674, 2023). "The aim of this study was to detect and compare the immunohistochemical expression of cleft candidate gene coded proteins (DLX4, MSX2, HOXB3, SHH, PAX7, SOX3, WNT3A, and FOXE1) in the non-syndromic unilateral cleft lip patient tissue and control group tissue." (PMID 33917041, 2021). "The available literature strongly indicates PAX7, PAX9, SHH, SOX3, WNT3A, and WNT9B to be strong candidate genes for cleft lip with or without cleft palate." (PMID 38227085, 2024).
Hypocalcemia (3 papers, 2017 to 2021). An abnormally decreased calcium concentration in the blood. "Thus, Sox3−/Y and Sox3+/− mice appear to have normal parathyroid function and normal responses to hypocalcaemia, and loss of Sox3 does not result in smaller parathyroids or HPT." (PMID 31961795, 2020). "Notably, however, SOX3 mutations have never been reported to cause hypocalcemia nor have SOX3 been linked functionally to calcium homeostasis in any organism." (PMID 28444561, 2017). "When challenged with a low calcium diet, all mice had hypocalcaemia, and elevated plasma PTH concentrations and alkaline phosphatase activities, and Sox3−/Y, Sox3+/−, uc482−/Y, and uc482+/− mice had similar plasma biochemistry, compared to wild-type littermates." (PMID 31961795, 2020). "However, absence of Sox3 expression that would occur in parathyroids of mutant mice with deletion of Sox3 did not result in hypocalcemia or HPT in Sox3-/Y mice." (PMID 31961795, 2020).
male infertility (3 papers, 2024). The inability of the male to effect fertilization of an ovum after a specified period of unprotected intercourse. "These functional impairments impede the proliferation of SOX3‐positive (SOX3+) progenitor spermatogonia, causing a failure of spermatogonial differentiation (KIT+) and meiosis initiation (SYCP3+), ultimately resulting in male infertility." (PMID 38837535, 2024).
orofacial cleft (3 papers, 2019 to 2024). A disorder of facial skeleton that is characterized by cleft lip and/or cleft palate that result in feeding, speech and hearing problems caused by failures during development. "Overall, there is a very limited amount of studies observing an association between SOX3 and orofacial clefts." (PMID 38227085, 2024). "The insertion of the super-enhancer may have disturbed the regulation of SOX3 expression during palate development, which may represent a causal variant associated with the orofacial clefting in this individual." (PMID 31801603, 2019). "The main aim of this specific study is to assess the presence of SHH, SOX3, WNT3A and WNT9B proteins by immunohistochemistry within the non-syndromic cleft-affected epithelium and connective tissue in non-syndromic orofacial cleft patient groups together with a comparison with the control group." (PMID 37366674, 2023). "However, whilst our results indicate no role for SHH and SOX3 in our study group, overall, we cannot exclude their involvement in orofacial cleft morphopathogenesis." (PMID 38227085, 2024).